SMURF2 (SMAD specific E3 ubiquitin protein ligase 2)
Diseases named in the same sentence as SMURF2 in open-access papers (continued):
Sharing a sentence is not in itself a finding about the gene and the disease.
breast carcinoma (continued). "Together, these data suggest that Smurf2 knockdown modulates the proliferation and invasiveness of breast cancer cells via regulating the PI3K-AKT signaling pathway and its downstream targets in a CNKSR2 dependent manner." (PMID 25191523, 2014). "All these data strongly support the role of Smurf2 in tumorigenesis, and subsequently blocking Smurf2 expression would be a rational strategy to treat breast cancer." (PMID 25191523, 2014). "Smurf2 silencing in human breast cancer cells resulted in a decreased focus formation potential and clonogenicity as well as in vitro cell migration/invasion capabilities." (PMID 25191523, 2014). "The purpose of the present study is to examine the effect of Smurf2 knockdown on the tumorigenic potential of human breast cancer cells emphasizing more on proliferative signaling pathway." (PMID 25191523, 2014). "In our study, we report for the first time that Smurf2 knockdown caused a marked decrease in the expression of CNKSR2 which in turn downregulates the proliferation and invasiveness properties of breast cancer cells via the PI3K-AKT signaling cascade." (PMID 25191523, 2014). "In the present study, we have evaluated the effect of Smurf2 silencing on colonigenicity, invasive properties, proliferation, and cell cycle in breast cancer cells using synthetic siRNA." (PMID 25191523, 2014). "Lymphomas and hepatocellular carcinomas are tumor types most commonly observed in two independent strains of Smurf2-null mice, while a few percent of Smurf2-null mice develop mammary carcinomas." (PMID 24485087, 2014). "Here we demonstrate that Smurf2 expression is downregulated in human breast cancer tissues, especially of the triple-negative subtype, and address the mechanism of Smurf2 downregulation in triple-negative breast cancer cells." (PMID 24485087, 2014). "Smurf2 has also been found to be upregulated in breast cancer tissue and cell lines as well as ovarian and prostate cancer cell lines." (PMID 20825672, 2010). "Silencing Smurf2 may reduce the tumorigenic properties of human breast cancer cells by lowering CNKSR2 expression levels." (PMID 39871432, 2025). "Furthermore, Smurf2 is also able to reduce the breast cancer cell migration and inhibit bone metastasis by degrading Smurf1 protein." (PMID 39871432, 2025). "However, the role of Smurf2 as an ubiquitin ligase in breast cancer, especially TNBC, remains to be further verified." (PMID 39871432, 2025). "Interestingly, SCRIBBLE and SMURF2 mRNAs are also over-expressed in several cases of basal VANGL2- or NOS1AP-amplified breast cancers but rarely in other subtypes." (PMID 36675340, 2023). "Overexpression of Smurf2 can promote invasion and metastasis in breast cancer." (PMID 35509688, 2022). "Smurf2 knockout promotes the migration and bone metastasis of breast cancer." (PMID 35509688, 2022). "SMURF2 silencing reduces the migration and invasion of breast carcinomas and colorectal cancer." (PMID 35017630, 2022). "Depletion of SMURF2 reduces the migration and invasion of breast carcinomas and CRC." (PMID 33418880, 2021). "Smurf1 and Smurf2 exert opposite roles in modulating breast cancer progression." (PMID 33718111, 2020). "Furthermore we observed that Smurf2 knockdown significantly decreases the tumorigenic potential of breast cancer cells." (PMID 29534682, 2018). "Moreover, they showed that SMURF2 silencing in human breast cancer cells decreases cell migration/invasion in vitro." (PMID 30619734, 2018). "87.5% of mammary carcinoma had elevated expression of Smurf2 compared to their normal counterparts." (PMID 29534682, 2018). "SMURF2−/− aging mice develop different types of tumors including breast cancer." (PMID 30619734, 2018). "Altogether, our findings reveal that Smurf2 is a novel positive regulator of CNKSR2 and suggest that Smurf2-CNKSR2 interaction may serve as a common strategy to control proliferation of human breast cancer cells by modulating CNKSR2 protein stability." (PMID 29534682, 2018).
breast carcinoma (continued). "The recent identification of Smurf2 as a suppressor of EMT in non-transformed mammary epithelial cells raises the important question of whether Smurf2 might regulate the malignant behavior of breast cancer cells." (PMID 28423498, 2017). "In addition, our data support a crucial role for the ubiquitin E3 ligase activity of Smurf2 in mediating the ability of sumoylated Smurf2 to suppress the invasive growth of breast cancer-derived organoids." (PMID 28423498, 2017). "Our study suggests that sumoylation may control Smurf2 function in breast cancer invasion and metastasis." (PMID 28423498, 2017). "Importantly, the E3 ubiquitin ligase activity is required for sumoylated Smurf2 to suppress the invasive growth of breast cancer-cell derived organoids." (PMID 28423498, 2017). "The findings that Smurf2 suppresses the invasive growth of breast cancer cell-derived multicellular structures raised the key question of how Smurf2 might be regulated." (PMID 28423498, 2017). "As SMURF2 is a potent inhibitor of TGF-β activity we investigated whether introducing a K734R mutant of SMURF2 into the TGF-β responsive metastatic breast cancer cell line MDA-MB-231 compromises the ability of SMURF2 to reduce TGF-β dependent migration." (PMID 26435193, 2015). "All these data strongly suggest the role of Smurf2 in breast cancer proliferation." (PMID 25191523, 2014). "Expression of Smurf2 is found to be dysregulated in many cancers including breast cancer." (PMID 25191523, 2014). "In order to address whether Smurf2 is essential for the proliferation of breast cancer epithelial cells, we next examined the proliferation rate of breast cancer cells after silencing of Smurf2 with siRNA." (PMID 25191523, 2014). "Our findings support the hypothesis that Smurf2 plays a conspicuous role in the tumorigenesis of breast cancer." (PMID 25191523, 2014). "Hence, to determine the appropriate model system for our in vitro study, we delineated the expression of Smurf2 protein in seven breast cancer cell lines." (PMID 25191523, 2014). "Thus Smurf2 knockdown probably downregulates proliferation of breast cancer cells in a CNKSR2 dependent manner by modulating the PI3K- PTEN-AKT-FoxO3a pathway." (PMID 25191523, 2014). "Ten widely-studied human breast cancer cell lines were examined for the expression of Smurf2." (PMID 24485087, 2014). "Furthermore, we demonstrated that silencing of Smurf2 downregulated the proliferation of breast cancer cells by modulating the PI3K- PTEN-AKT-FoxO3a pathway via the scaffold protein CNKSR2 which is involved in RAS-dependent signaling pathways." (PMID 25191523, 2014). "Moreover, we observed that expression of cyclin D1, a critical regulator of G1 phase progression of breast cancer cells was found to be significantly downregulated in Smurf2 siRNA treated cells." (PMID 25191523, 2014). "First, we used a focus formation assay to test whether silencing Smurf2 in breast cancer cells affects the clonogenic potential, which correlates with tumor formation in vivo." (PMID 25191523, 2014). "We therefore conclude that targeting the Smurf2-CNKSR2- PI3K/AKT functional axis could be used as a potential preventive/therapeutic strategy in the management of breast cancer in humans." (PMID 25191523, 2014). "Furthermore, the inhibitory effect of Smurf2 on breast cancer cell proliferation was confirmed by using proliferation markers such as PCNA and Ki67 which are important regulators of proliferative indices." (PMID 25191523, 2014). "Human breast cancer tissues (47 samples expressing estrogen receptor (ER) and 43 samples with triple-negative status) were examined by immunohistochemistry for the expression of Smurf2." (PMID 24485087, 2014). "Hence we were interested to determine the effect of Smurf2 knockdown on proliferation of breast cancer cells by analysing the focus formation and colony formation ability in soft agar compared with cells transfected with the control siRNA." (PMID 25191523, 2014).
breast carcinoma (continued). "SMURF1 also shows tumor-promotor activity in breast cancer cells where the ubiquitination function of SMURF2 can promote SMURF1 degradation and, consequently, may rescue important tumor suppressive substrates of SMURF1 to prevent malignant migration of tumor cells." (PMID 36918822, 2023). "Owing to the fact that PI3K-AKT signaling is hyperactivated in various human cancers and that Smurf2 also regulates cellular transformation, our results indicate that Smurf2 may serve as a potential molecule for targeted cancer therapy of certain tumour types including breast cancer." (PMID 25191523, 2014). "Since cyclin D1 was reported to play a significant regulatory role during progression through the G1 phase of breast cancer cells, we next examined whether the expression of cyclin D1 was responsible for the G0/G1 cell cycle arrest in Smurf2 siRNA-treated cells." (PMID 25191523, 2014). "It will be important to determine whether Smurf2 can interact with CNKSR2 which possess a PPxY sequence in its structure which is necessary for interaction with WW domain of Smurf2 and whether its levels correlate with each other in human breast cancer progression models." (PMID 25191523, 2014). "In summary, studies from our laboratory have shown that silencing of Smurf2 with siRNA resulted in significant inhibition of focus formation potential, anchorage-independent growth capability, migration, invasiveness, and proliferation in breast cancer cells by a possible interaction with CNKSR2." (PMID 25191523, 2014). "Smurf2 promotes ribosomal protein L35A (RPL35A) polyubiquitination and degradation, leading to inhibition of proliferation and cell-cycle progression in breast cancer." (PMID 40978141, 2025). "Another PROTAC tractable target is Rac Family Small GTPase 1 (RAC1), inducing chemoresistance of breast cancer, interacts with co-opted E3 ligases MDM2 and XIAP, and potentially novel E3 ligases, ITCH and SMURF2." (PMID 37845222, 2023). "A previous study showed that TRAF4 promoted the degradation of SMAD ubiquitination regulatory factor 2 (SMURF2) by increasing the polyubiquitination of SMURF2 to regulate pro-oncogenic TGF-β signaling and promote breast cancer metastasis." (PMID 36535926, 2022). "USF2 has been reported to downregulate Smurf1 and Smurf2, thereby regulating the TGF-β pathway in breast cancer." (PMID 35255935, 2022). "Smurf2 can be SUMOylated at K29 and K369, and its SUMOylation contributes to the downregulation of TGFβ signaling and inhibits the EMT in breast cancer cells." (PMID 33968766, 2021). "SMURF2 acts as a ubiquitinating enzyme for SMURF1 and hence promotes degradation of its sister protein in the early stages of breast cancer." (PMID 33418880, 2021). "We employed two short hairpin RNAs (shRNAs) targeting distinct sequences within Smurf2, which individually or in combination led to efficient knockdown of endogenous Smurf2 in MDA-MB-231 breast cancer cells." (PMID 28423498, 2017). "Concomitantly, we performed numerous experiments including the wound healing assay, migration assay, and invasion assay to assess the effect of Smurf2 knockdown on invasive potential of MCF7 and MDA-MB-231 breast cancer cells." (PMID 25191523, 2014). "In this study we demonstrate that human TNBC tissues express significantly lower levels of Smurf2 protein relative to normal mammary tissues, ductal carcinomas in situ (DCIS) and ER+/PR + breast cancer tissues." (PMID 24485087, 2014). "For example, Smurf2 has been shown to target ring finger protein 11 (RNF11), Smurf1, and connector enhancer of kinase suppressor of Ras 2 (CNKSR2) for ubiquitination and degradation in breast cancer." (PMID 40978141, 2025). "TRAF4 modulates canonical signaling in breast cancer cells by ubiquitinating SMURF2 for destruction and mediates non-canonical signaling in a Traf6-independent manner, stabilizing TGFBR at the plasma membrane." (PMID 38313020, 2024).
breast carcinoma (continued). "Two other genes involved in PCP, ligand WNT11 and ubiquitin ligase SMURF2, are amplified in smaller percentages of breast cancer cases (WNT11: in 5.2% of cases in TCGA and 6.7% of cases in METABRIC; SMURF2: in 6.2% of cases in TCGA and 8.1% of cases in METABRIC)." (PMID 36675340, 2023). "Thus, SMURF1 and SMURF2 inducers can be considered as effective treatments for HCC and breast cancer, respectively." (PMID 36918822, 2023). "These IHC findings, together with our data showing that in certain types of cancer cells, including breast cancer, KAP1 is stabilized by SMURF2, may imply that elevated expression of KAP1 in certain tumors emanates from the heightened expression of SMURF2." (PMID 35406379, 2022). "The conducted immunohistochemical studies showed that the reciprocal relationship between the expression of SMURF2 and KAP1 also exists in human normal and breast cancer tissues and suggested that this relationship may be disrupted by the carcinogenic process." (PMID 35406379, 2022). "The contextual nature of KAP1 regulation by SMURF2 was also evident from the examination of several other untransformed and cancer cell strains, including mammary epithelial MCF-10A cells, breast carcinoma MDA-MB-231 cells, and prostate adenocarcinoma PC3 cells." (PMID 35406379, 2022). "There, TGFβ-mediated activation of non-canonical PIP3/AKT/FOXO3a was SMURF2-dependent; upon SMURF2 inactivation, proliferation of breast cancer cells decreased." (PMID 33418880, 2021). "We postulate that the negative effect of Smurf1 on TGF-β signaling is completely offset by the downregulation (in protein levels and ubiquitin ligase activity) of Smurf2, with the final result being enhanced TGF-β signaling that promotes breast cancer progression." (PMID 33718111, 2020). "Smurf2 promotes the ability of tumor cells to metastasize by the regulation of a signaling pathway that is independent of Smads, Rap1B and RhoA in breast cancer cells." (PMID 33114139, 2020). "In breast cancer cells, the mechanism of Smurf1 ubiquitination mediated by Smurf2, as well as Smurf1-induced mechanisms independent of TGF-β signaling, need to be further studied." (PMID 33718111, 2020). "To test this hypothesis, we treated breast carcinoma MCF7 cells with CRM1 inhibitor leptomycin B (LMB) and monitored the nucleo-cytoplasmic translocation of SMURF2 in these cells using western blot analysis." (PMID 31003445, 2019). "Further, expressions of SMURF2 as well as of PP1c neither correlated with miR‐128‐3p expression nor were these genes differentially expressed in the different breast cancer subtypes (data not shown)." (PMID 30004628, 2018). "Indeed, we observed that knockdown of Smurf2 downregulated the expression of CNKSR2 and reduced the proliferative potential of human breast cancer cells." (PMID 29534682, 2018). "The aim of this study was to investigate whether the interaction between Smurf2 and CNKSR2 has any significant role in the post transcriptional regulation of CNKSR2 expression in breast cancer." (PMID 29534682, 2018). "Contrary to this speculation, it was consistently observed that CNKSR2 protein levels were decreased by siRNA mediated Smurf2 depletion in MDA-MB-231 and MCF7 breast cancer cell lines, SW480 colon cancer cell line and SCC131 oral cancer cell line." (PMID 25191523, 2014). "Protein levels of Smurf2 were found to be downregulated in human lymphoma and breast cancer tissues relative to non-cancer tissues." (PMID 24485087, 2014). "Besides, a combination treatment by NEDD4-1 and WWP1 inducers for melanoma cancer, NEDD4-1 and ITCH inhibitors for prostate cancer, NEDD4-1 and SMURF1 for the HCC, as well as SMURF2 inducers and ITCH inhibitors for the breast cancer can be considered as the effective therapeutic approaches." (PMID 36918822, 2023).
breast carcinoma (continued). "Conversely, Smurf2 knockdown resulted in a marked decrease in the protein level expression of CNKSR2 by facilitating enhanced polyubiquitination and proteasomal degradation and reduced the proliferation and clonogenic survival of MDA-MB-231 breast cancer cell lines." (PMID 29534682, 2018). "Importantly, Smurf2 shRNAs increased the proportion of invasive breast cancer cell-derived organoids, even in the absence of TGFβ." (PMID 28423498, 2017). "Furthermore, Smurf2 expression was reported to be elevated in breast human cancer tissues and cell lines, and its stable overexpression promoted the ability of malignant MCF10CA1 breast cancer cells, derived from premalignant human breast epithelial MCF10A, to metastasize in an in vivo model." (PMID 33114139, 2020). "We then examined human breast cancer cell lines and non-transformed mammary epithelial MCF-10A cells by immunoblotting for Smurf2." (PMID 24485087, 2014). "Although a previous research has reported that SMURF1 can ubiquitinate HER2 when triggered by a compound JAC1, SMURF1 targeted by TRAF4 has not been validated, whereas SMURF2 has been shown to be targeted by TRAF4 for promoting TGF-beta signaling and facilitating breast cancer metastasis." (PMID 35864174, 2022). "Contrary to this speculation, it was consistently observed that NEDD9 protein levels were decreased by siRNA-mediated Smurf2 depletion in HeLa cervical carcinoma cells and CN34 mammary carcinoma cells, and U2OS osteosarcoma cells (data not shown)." (PMID 20825672, 2010).